IGF1 (insulin like growth factor 1)
Diseases named in the same sentence as IGF1 in open-access papers (continued):
Sharing a sentence is not in itself a finding about the gene and the disease.
tumor (continued). "CR promotes metabolic reprogramming by inducing a state of low energy availability that sensitizes tumor cells, which, according to the literature, is due to the inhibition of crucial oncogenic pathways such as IGF-1 and insulin signaling." (PMID 41514622, 2025). "Our results combined the Ki-67 labeling index, SSTR 2 and SSTR 5 expression, postoperative values of GH and IGF-1 and postoperative maximum tumor diameter." (PMID 40276548, 2025). "Treatment with an IGF1 neutralization antibody decreased tumor formation, with tumors appearing in only seven out of nine mice." (PMID 40659611, 2025). "The proportion of tumor-related etiology was lower in the group with upper-normal IGF-1 SDSs compared to those with lower-normal levels; however, the difference was not significant." (PMID 40076636, 2025). "IGF-1 is well recognised as a tumour-promoting growth factor and is involved in tumour metastases, but it is recognised as being integral in extracellular tissue modelling through increasing collagen metabolism and fibroblast growth." (PMID 39796177, 2025). "Survivin, an apoptosis inhibitor, is upregulated by IGF1 signalling, contributing to therapy resistance and sustained tumour survival." (PMID 39796756, 2025). "Tumor weight and tumor-to-total liver weight ratio were both increased by IGF1 treatment and significantly reduced by linsitinib treatment compared to controls." (PMID 41275311, 2025). "Jenkins and Besser have previously suggested a potential oncogenic link between elevated IGF-1 and tumor proliferation." (PMID 41479497, 2025). "In ESCC patients, tumour expression of IGF-1 RNA in the top versus the bottom quartile expression groups was associated with worse overall survival (OS) (HR, 1.876; 95% CI 1.2007 – 2.915, p = 0.005)." (PMID 40615716, 2025). "This aligns with existing evidence suggesting that increased IGF-1 bioavailability promotes mitogenic and anti-apoptotic effects, contributing to tumour growth." (PMID 40493660, 2025). "Tumor growth was further enhanced in the CAF-oeIGF1 group, while both CAF-sgIGF1 and CAF + α-IGF1 nAb groups showed significantly reduced tumor sizes compared to CAF + oeIGF1 group, indicating a tumor-promoting function of CAF-derived IGF1." (PMID 41275311, 2025). "Partial tumor resection was performed three months after the initial visit to relieve optic chiasm compression and normalize insulin-like growth factor 1 (IGF-1) levels, as whole tumor resection extending into the cavernous sinus was deemed high-risk." (PMID 40895665, 2025). "IGF1 has been shown to respond to hypoxic conditions, contributing to extracellular matrix remodelling, tumour invasion, and metastasis." (PMID 39796756, 2025). "Simultaneously, IGF-1 encourages the progression of an immunosuppressive microenvironment by promoting the expansion of Tregs and MDSCs, thereby facilitating tumor cell immune evasion." (PMID 41164182, 2025). "Concurrently, the IGF1 signaling pathway is integral to tumor cell proliferation, survival, and invasion." (PMID 41333209, 2025). "UMAP-based cell-type mapping further revealed that IGF1, a secreted factor with pleiotropic effects in the tumor microenvironment, was predominantly expressed in the CAF-C7 subpopulation, suggesting a central role for CAF-C7 in non-R0 tumors." (PMID 41463024, 2025). "GLP-1 RAs improve systemic glucose homeostasis and reduce circulating insulin levels, potentially disrupting insulin/IGF-1 signalling pathways frequently co-opted by tumour cells." (PMID 41300804, 2025). "IGF-1, in particular, accelerates cell cycle progression while preventing programmed cell death, facilitating tumor progression." (PMID 40995175, 2025). "Over three to eight months, pasireotide reduced tumour volume in all patients and improved GH and IGF-1 levels." (PMID 40216609, 2025). "MD has also been shown to result in a reduction of CRP and IGF-1 which, at high levels, induce a pro-tumour metabolic profile." (PMID 41335382, 2025).
tumor (continued). "As a potential mechanism of action, higher levels of angiogenic factors such as VEGF, IGF-1 or leptin were observed in obese patients, leading to chemoresistance and enhanced tumor proliferation." (PMID 40217461, 2025). "I consider first-generation SSAs treatment post-surgery in any symptomatic patient with above normal IGF-1(>=1.5-2ULN) and an unresectable tumor residual." (PMID 40575269, 2025). "Obesity contributes to carcinogenesis through mechanisms such as chronic inflammation, insulin resistance, and elevated levels of growth factors like IGF-1 and leptin, which promote tumor growth and progression." (PMID 40428567, 2025). "Combining the four parameters, ki-67, SSTR 2, SSTR 5, GH, IGF-1 and the maximal tumor diameter (postoperative values), we established a prediction model with an AUC of 0.924 and relatively high sensitivity and specificity." (PMID 40276548, 2025). "The breakdown of this system leads to the release of IGF1 from the complex, and this process (accumulation of IGF1) can facilitate cell migration toward the tumor." (PMID 39854135, 2025). "Simultaneously, IGF1-mediated angiogenesis establishes a highly vascularized niche that promotes tumor progression." (PMID 41463024, 2025). "I consider radiotherapy as a second-line treatment post-surgery for any symptomatic patient with above normal IGF-1(≥1.5–2 ULN) with unresectable residual tumor." (PMID 40575269, 2025). "I consider repeat surgery for in any symptomatic patient with above normal IGF-1(≥ 1.5–2 ULN) when there is a potentially resectable tumor remnant after the first pituitary surgery." (PMID 40575269, 2025). "DAs can bind to dopamine receptor subtype 2 in GH adenomas, reducing the secretion of GH and IGF-1, and inhibiting tumor cell proliferation." (PMID 41550875, 2025). "Given the critical roles of these molecules in tumor biology, this study aimed to retrospectively investigate the association of serum VEGFC, VEGFR-3, and IGF1 levels with metastasis and prognosis in a cohort of NPC patients." (PMID 41333209, 2025). "In hormone-sensitive tissues, leptin interacts with insulin and IGF-1 signalling, forming an endocrine-oncogenic triad that supports tumour progression." (PMID 41586225, 2025). "In this 48-year-old patient, for whom neurosurgery was not feasible due to the macroadenoma's extension, treatment with pasireotide LAR successfully improved prolactin, GH and normalised IGF-1 levels, while tumour size remained stable." (PMID 41287839, 2025). "Subsequent multivariate Cox regression confirmed the statistical significance of IGF-1 (low vs. high) and tumour volume, with the overall model's significant robustness." (PMID 39624154, 2025). "In our initial HNSCC analysis, ~ 50% of the (universal) PI16 + fibroblast cluster from tumour samples were labelled as IGF1 + CAF in the larger PCFA dataset." (PMID 39757146, 2025). "IGF-1 and tumor volume significantly impacted OS (HR: 6.9 and 1.004, p = 0.014 and 0.0022, respectively)." (PMID 39624154, 2025). "In subcutaneous xenograft mice, KDM6A depletion significantly promoted tumor growth, and treatment with the IGF1 neutralization antibody reduced this tumor-promotion effect." (PMID 40659611, 2025). "IGF1-Ec has been observed to antagonise PTEN’s tumour-suppressive functions by activating downstream pathways such as PI3K/AKT and MAPK, which promote cell proliferation and inhibit apoptosis." (PMID 39796756, 2025). "Patient 4, 52-year-old female, despite initial side effects on pasireotide, achieved normalisation in IGF-1 levels and resolution of active symptoms, with a significant reduction in tumour size." (PMID 41287839, 2025). "The Western diet, characterized by high intakes of red meat, processed foods, and refined sugars, exacerbates insulin and IGF-1 signaling, promoting tumor growth and progression." (PMID 40428567, 2025). "This indicates that tumor-derived GSLs, along with the IGF-1 signaling pathway, play a significant role in modulating osteoclast activity." (PMID 40565082, 2025).
tumor (continued). "Eleven months after the initial surgery, persistently elevated IGF-1 levels necessitated a second resection of the residual tumor." (PMID 40895665, 2025). "Tumor cells in bone lesions activate osteoclasts, leading to bone matrix degradation and the release of growth factors (e.g., TGF-β, IGF-1), which in turn stimulate tumor growth." (PMID 40837013, 2025). "Metabolic parameters, plasma biomarkers (including leptin, insulin, IGF-1, adiponectin, and estrone), mammary gland histology, tumor incidence, and gene expression profiles were longitudinally evaluated." (PMID 40806434, 2025). "Conversely, Trop-2 has been shown to abrogate NSCLC tumor cell growth through binding to and blocking IGF-1 signaling." (PMID 40233061, 2025). "These splicing events highlight the critical role of IGF1 isoforms in shaping the tumour microenvironment, as discussed in detail in the next section." (PMID 39796756, 2025). "And IR is associated with increased levels of IGF-1, which activates the IGF-1 receptor or promotes the production of vascular endothelial growth factor, thereby promoting tumor cell proliferation and angiogenesis." (PMID 40756516, 2025). "The limited number of published studies conducted to date in adults suggests a significant role of α-Klotho as a tumor suppressor, partially through the inhibition of the IGF-1 and Wnt/β-catenin signaling pathways." (PMID 38792509, 2024). "The clinical implications of IGF-1 research extend beyond its direct role in tumor biology, offering potential for broader therapeutic applications in BC management." (PMID 39273251, 2024). "Elevated insulin levels can enhance tumor growth through the insulin-like growth factor 1 (IGF-1) pathway, a signaling cascade known to promote cellular proliferation and inhibit apoptosis (programmed cell death)." (PMID 39518104, 2024). "Higher levels of IGF-1 or IGF-1R are linked to enhanced cell proliferation, skin hyperplasia, and tumor formation." (PMID 39638246, 2024). "Among them, increasing tumor size possesses the highest score of 3, then followed by score 2 factors: T2 magnetic resonance intensity, younger age, Ki-67 > 3%, higher baseline GH/IGF-1 levels, and tumor volume (T4/T5)." (PMID 39224564, 2024). "Plasmodium infection also inhibits tumor angiogenesis by blocking the IGF-1/MMP9 signaling pathway of TAMs in tumor tissue through the metabolite hemozoin of the parasite." (PMID 38807760, 2024). "In the same tumor model, the cytotoxic activity of NK cells was enhanced following the over-expression of miR-486-5p, an inducer of IGF1 protein expression." (PMID 38420122, 2024). "IGF-1Ec production after proteolytic cleavage leads to the release of the mature IGF-1 and PEc, both molecules inducing tumor progression via different receptors." (PMID 39273251, 2024). "Their study showed that elevated levels of IGF-1/2 are expressed by BRCA-associated TAMs, which stimulates insulin/IGF-1 receptor signaling in tumor cells." (PMID 38341519, 2024). "In melanoma and breast cancer mouse models, it has been observed that mice fed a low-protein diet (4% kcal protein) exhibit reduced IGF-1 levels and slower tumor progression compared to those fed a high-protein diet (18% kcal protein)." (PMID 38462638, 2024). "For example, our prior studies indicate that in epithelial ovarian cancer, Tie2+TAMs recruited to tumor ascites by Angiopoietin-2 (Ang2) enhance endothelial function and tumor angiogenesis via IGF1-induced signaling." (PMID 38185636, 2024). "IGF1 was at lower levels in tumor tissues than in adjacent tissues, possibly because of its association with lower survival." (PMID 39042294, 2024). "Future studies with higher dosages of the long-acting pegylated GHRAs used in this study can, in addition to blocking direct GH actions on the tumor, also suppress systemic IGF1 levels." (PMID 39000545, 2024).
tumor (continued). "Compared with those in adjacent tissues, the expression levels of CDKN2A, BIRC5, and SPP1 were significantly upregulated in tumor tissues (p < 0.05), while the expression of IGF1 was considerably downregulated (p < 0.001)." (PMID 39042294, 2024). "The IGF-1 signaling system is integral not only to tumor growth but also to maintaining normal cellular functions." (PMID 39273251, 2024). "Continuous values (age, tumor size, preoperative GH level, preoperative IGF-1 level) were dichotomized by selecting an appropriate standard value with reference to each median value." (PMID 39170435, 2024). "A mouse model subsequently confirmed this finding by demonstrating enhanced tumour growth and decreased infiltration of T cells within the tumour with IGF1 overexpression." (PMID 39061159, 2024). "In the tumor microenvironment, IGF-1 and its isoforms play significant roles in cell proliferation and survival." (PMID 39273251, 2024). "Lastly, experimental cancer therapeutics are exploring synthetic molecules mimicking IGFBP’s IGF-1 binding properties, though their effectiveness is limited by IGF-1 independent and sometimes tumor-promoting actions of IGFBPs." (PMID 39273251, 2024). "Bone is also a rich source of matrix‐stored growth factors such as transforming growth factor β (TGF‐β) and insulin‐like growth factor 1 (IGF1) which can interact with tumour cells in bone, affecting tumour growth and dormancy." (PMID 39385703, 2024). "Multiple studies corroborate the pivotal role of the IGF-1/IGF-1R signaling pathway in tumor progression and drug resistance." (PMID 38413558, 2024). "The increase in insulin levels can act as a direct growth-promoting signal and the elevated free bioactive insulin-like growth factor 1 (IGF1) can indirectly alter the cellular environment favorably for tumor development." (PMID 38255203, 2024). "In hepatic carcinogenesis, TUG1 (lncRNA) adsorbs miR-1-3p, promoting IGF1 expression and tumor proliferation." (PMID 38191389, 2024). "In contrast to the apparent malignant effects of IGF-1 in the tumor microenvironment, high levels of IGF-1 in the circulation were associated with more favorable outcomes." (PMID 38396692, 2024). "With elevated IGFBP-2 concentrations, the bioavailability of IGF-1 decreases, impeding its transport and potentially weakening its impact on tumor progression." (PMID 39290325, 2024). "CLL cells and tumor-associated stromal cells also produce and secrete FGF-2, TNF-α, CXCL-12, CXCL-2, NGAL, IGF-1, progranulin, and angiogenin." (PMID 39796700, 2024). "Preoperative clinical factors that predicted the remission of GH-producing pituitary tumor include preoperative GH level, IGF-1 level, tumor size, primary or reoperation, age, and higher Knosp grade." (PMID 39170435, 2024). "While both regulate IGF activity, IGFBP-3 predominantly acts as a tumor suppressor by inhibiting IGF-1 and IGF-2 from activating IGF-1R, thus reducing cell proliferation and promoting apoptosis." (PMID 39585162, 2024). "The positive effects on GH/IGF-1 secretion and tumor mass are deemed more crucial, with any potential deterioration in glycemic control being considered a separate concern." (PMID 38809458, 2024). "IGF1R encodes a high affinity receptor of insulin-like growth factor 1 (IGF1) with tyrosine kinase activity, which triggers downstream signaling pathway promoting cellular proliferation, tumor transformation, and the survival of malignant cells." (PMID 39542983, 2024). "It highlights key insights, such as tumour associations, prognostic indicators (e.g. chronic liver disease) and an 88% positivity rate for IGF2:IGF1 ratio>10." (PMID 38411039, 2024). "Factors that include histology sparsely granulated tumor, MRI T2 intensity, younger age, Ki-67 > 3%, higher baseline levels of GH/IGF-1, tumor volume (T4/T5), and increased tumor size." (PMID 39224564, 2024). "In the combination cultures, fenretinide suppressed the proliferative effect of IGF-1 on tumor cells." (PMID 38919490, 2024).
tumor (continued). "AC supplementation significantly suppressed tumor incidence and multiplicity in females (p < 0.05) and reduced IGF-1 and Wnt/β-catenin signaling (p < 0.05)." (PMID 39125288, 2024). "In vitro and ex vivo experiments further demonstrated that APOE+/CD163+ macrophages promote tumor epithelial–mesenchymal transition via insulin-like growth factor 1 (IGF1)–IGF1 receptor interactions, suggesting critical molecular biomarkers for AM." (PMID 39408752, 2024). "The promising results obtained from the IGV001 and VOKVAC phase 1 clinical trials are the demonstration that manipulating the tumor immune microenvironment through targeting the IGF1/IGF1R axis is safe and feasible." (PMID 38420122, 2024). "B cells isolated from GB patient samples have been shown to promote tumor cell proliferation and migration through the secretion of growth factors such as insulin-like growth factor-1 (IGF-1) and hepatocyte growth factor (HGF)." (PMID 38523646, 2024). "The almost complete suppression of FSH (97.8%) in all patients co-treated with E4 is therefore a significant anti-tumor effect, similar to the significantly enhanced suppression of the mitogen IGF-1." (PMID 39408055, 2024). "Stimulation with CG triggers the release of insulin-like growth factor-1 (IGF-1) from tumor cells, which, via paracrine/autocrine signaling, activates the IGF-1 receptor (IGF-1R)." (PMID 39143953, 2024). "IGF-1 levels resulted central for evaluating resistance to fgSRLs, that should be defined considering also symptomatic clinical response, degree of tumor shrinkage and complications, using clinician- and patient-reported outcome tools available." (PMID 38809458, 2024). "GH is one of the main regulators of IGF1 production in the liver and other tissues and, accordingly, GH-IGF1 exerts tumor-promoting functions." (PMID 38892104, 2024). "Overall, data collected in vivo demonstrated that Mir15aKO favors tumor progression in nutrient restriction, pointing to a critical role of IGF1 signaling in the adaptive mechanisms of PDAC." (PMID 38342897, 2024). "Several predictors of resistance have been described and include the patients’ gender, age, initial GH and IGF-1 levels, tumor volume, tumor hyperintensity on T2-weighted magnetic resonance imaging, and the expression of somatostatin receptor subtypes." (PMID 38809458, 2024). "By enhancing MMP-9 expression, TAMs are associated with elevated VEGF-A levels, inducing tumor growth and tumor angiogenesis in HCC, mediated by the type 1 insulin-like growth factor (IGF-1) signaling pathway through the PI3-K and MAPK pathways." (PMID 39796695, 2024). "We did not observe the relation between CNA status and other clinical/demographical features including patient’s age at surgery and sex, GH1 and IGF-1 in patients, as well as tumor size and invasive growth status." (PMID 39497133, 2024). "In contrast with these observations, calorie restriction decreases tumor growth in mouse models, attributed to reduced insulin and IGF-1 levels and enhanced tumor immunity." (PMID 38831236, 2024). "Compared with Mph_04_SPP1, Mph_03_DAB2 exhibiting higher levels of FOLR2, SLC40A1, and IGF1, which are genes specifically expressed by some reported TAMs that known to play a role in promoting tumor progression 57-59." (PMID 39239526, 2024). "CDKN2A, BIRC5, and SPP1 expression levels were significantly upregulated in tumor tissues (p < 0.001), while IGF1 expression was considerably downregulated (p < 0.001)." (PMID 39042294, 2024). "Subsequent medical therapy aims to control tumor growth, inhibit GH hypersecretion, normalize IGF-1 levels, and reduce the burden of comorbidities." (PMID 38809458, 2024). "For example, SPP1+TAMs promoted tumor growth and proliferation by secreting collagen and insulin-like growth factor-1 (IGF-1)." (PMID 38347955, 2023).